ENSG00000252228
Synonyms: LOC124900227
Gene: Small nucleolar RNA gene on chromosome 6 (30,132,805 to 30,132,966, reverse strand). Ensembl gene ENSG00000252228.
Gene Ontology:
Biological process: RNA processing
Cellular component: nucleolus
Homologues: Paralogues in human: SNORA48 (62% identical), SNORA48B (62% identical).